EGFR (epidermal growth factor receptor)
Diseases named in the same sentence as EGFR in open-access papers (continued):
Sharing a sentence is not in itself a finding about the gene and the disease.
lung cancer (continued). "We reasoned that the landscape captured in this way for resistance pathways/complexes in EGFR mutant lung cancer might be relevant as cancer persistence mechanisms." (PMID 38658677, 2024). "EGFR inhibitors promote macrophage phagocytosis of EGFR mutant lung cancer cells." (PMID 38483480, 2024). "Based on these findings, it is reasonable to explore whether the same regulatory connection between DUSP22 and EGFR plays a significant role in repressing the development and progression of EGFR-driven lung cancer." (PMID 38877005, 2024). "Given these divergent models, we applied genome-wide analytic strategies to test whether other genetic mechanisms may explain EGFR-mutant lung cancers presenting with multiple primary lesions." (PMID 39406916, 2024). "Taken together, these findings imply that EGFR/HER2 inhibitors are possible therapeutic choices for patients with BCAR4 fusion-positive lung cancer, even in the absence of EGFR mutations." (PMID 38919532, 2024). "At present, the third-generation EGFR-TKIs have been recommended by the authoritative lung cancer diagnosis and treatment guidelines of the United States and China as the first choice for the treatment of NSCLC with EGFR-sensitive mutation and T790M resistance mutation." (PMID 39308869, 2024). "In addition, NSCLC cells often develop resistance to osimertinib, a newer generation EGFR TKI used as a first- or second-line treatment for lung cancer." (PMID 38540176, 2024). "One of the key proteins involved in lung cancer is the epidermal growth factor receptor (EGFR)." (PMID 39619439, 2024). "Epidermal growth factor receptor (EGFR) is a critical therapeutic target used to treat lung cancer." (PMID 39264588, 2024). "East Asian patients with lung cancer exhibit a higher prevalence of EGFR mutations, and studies have indicated a strong concordance between plasma- and tissue-based NGS for detecting EGFR mutations." (PMID 39125693, 2024). "Compared to our previous meta-analysis about the application of radiomics in prognosing lung cancer treated with epidermal growth factor receptor tyrosine kinase inhibitors (EGFR-TKI), the quality of the studies about immunotherapy was better, except in the study-confounding domain." (PMID 38339369, 2024). "In addition, osimertinib can effectively cross the blood–brain barrier and is effective in patients with brain metastases (including meningeal metastases) from lung cancer, which is a major advantage over other small-molecule EGFR inhibitors." (PMID 38674402, 2024). "BA could chemosensitize wt-EGFR lung cancer cells to gefitinib/osimertinib through direct binding to EGFR, triggering PI3K-AKT-mTOR axis-mediated autophagic cell death, consequently inducing cell cycle arrest and causing marked tumor regression in vivo." (PMID 38764025, 2024). "In addition to these advancements, the identification of four high-frequency mutated genes (NOTCH1, IGF2, EGFR, and PTCH1) through CTCs NGS holds promise for the early diagnosis of lung cancer." (PMID 38561776, 2024). "Patients with EGFR mutation-positive lung cancer who are non-responders to first-line EGFR-TKI therapy have been suggested to have decreased overall survival (OS) compared with responders." (PMID 39156250, 2024). "Forward genetic screens represent powerful tools to identify mechanisms of drug resistance – here we used genome-scale loss (CRISPRn) and gain (CRISPRa) of function CRISPR screens to identify genes and pathways complicit in resistance (or persistence) to EGFR inhibitors in EGFR mutant lung cancer." (PMID 38658677, 2024). "As lapatinib is not routinely used in lung cancer patients, we further compared the EGFR mutation in different risk groups." (PMID 38317133, 2024).
lung cancer (continued). "Additionally, gefitinib triggers autophagy-mediated degradation of EGFR in lung cancer cells resistant to TKIs as a protective mechanism, thereby promoting the development of resistance driven by T790M mutation." (PMID 38794196, 2024). "In recent years, the prognosis of lung cancer has depended on the presence or absence of EGFR mutation and ALK fusion protein." (PMID 37747688, 2024). "However, several clinical trials have not shown significant benefits from PD-1/PD-L1 blockade alone or with an EGFR TKI in EGFR mutant lung cancer patients." (PMID 38877005, 2024). "EGFR amplification was predominantly found in lung cancer (3.5%)." (PMID 39682116, 2024). "Therefore, targeting the HGF/MET axis in EGFR TKI-resistant lung cancer has emerged as a promising strategy to overcome EGFR TKI resistance." (PMID 38338342, 2024). "However, these secondary EGFR mutations appear less frequently in CNS resistance samples from EGFR-mutant lung cancer patients." (PMID 38806586, 2024). "The identification of EGFR as an oncogene has led to the development of anticancer therapeutics directed against EGFR (called “EGFR inhibitors”, EGFRi), including gefitinib, erlotinib, afatinib, brigatinib, and icotinib for lung cancer, and cetuximab for colon cancer." (PMID 38337403, 2024). "This may elucidate the potential pathophysiological mechanisms underlying subpleural fibrotic ILA, which is mostly accompanied by wild-type EGFR lung cancer." (PMID 38783331, 2024). "Besides the aberrant DNA methylation of EGFR, our study revealed that other methylation changes also contribute to lung cancer initiation and development." (PMID 39036344, 2024). "However, its potential to address EGFR-mutant NSCLC represents a significant advancement in personalized medicine for lung cancer patients." (PMID 38611728, 2024). "In this study, we did not discuss the impact of kinship status on EGFR-mutated or ALK-mutated lung cancers." (PMID 38721224, 2024). "The reason for this difference is yet unclear, but it may be related to differences in DDR mechanisms or other mechanisms of mutagenesis and could be an important clue to the etiology of EGFR-mutant lung cancer." (PMID 39052387, 2024). "Additionally, Tu and colleagues demonstrated that incense smoke can sensitize lung cancer cells to epidermal growth factor receptor (EGFR) tyrosine kinase inhibitors (TKIs) by inducing amphiregulin (AREG) expression." (PMID 39725665, 2024). "Additionally, CANA significantly reduced the anticancer activity of L858R/T790M EGFR kinase, thereby inhibiting the efficacy of EGFR TKIs in resistant lung cancer cells." (PMID 38595915, 2024). "However, resistance to EGFR inhibitors, such as erlotinib, presents a significant challenge in treating lung cancer." (PMID 39897079, 2024). "Here, we present a 10XGenomics scRNA-seq experiment, providing a controlled heterogeneous environment using lung cancer cell lines characterised by the expression of seven different driver genes (EGFR, ALK, MET, ERBB2, KRAS, BRAF, ROS1), leading to partially overlapping functional pathways." (PMID 38307867, 2024). "To examine whether BA could potentiate EGFR-TKIs in lung cancer cells expressing wild-type EGFR gene, we evaluated the inhibitory effect of combination treatment with BA and EGFR-TKIs (gefitinib and osimertinib)." (PMID 38764025, 2024).
lung cancer (continued). "Furthermore, the mechanism by which ADAMTS18 increases the sensitivity of lung cancer cells to cisplatin is that ADAMTS18 acts as an inhibitor of epidermal growth factor receptor/protein kinase B (EGFR/AKT) signaling antagonist." (PMID 38482210, 2024). "In contrast, ICIs occasionally exert sustained tumor inhibition in some EGFR-mutant lung cancers." (PMID 38347279, 2024). "EGFR and ALK mutations are critically relevant for prediction of treatment response in lung cancer." (PMID 38572163, 2024). "Importantly, our data revealed a consistent dephosphorylation-based regulation between DUSP22 and EGFR in different lung cancer cell lines harboring wild-type (WT) or mutant EGFR genes." (PMID 38877005, 2024). "Nevertheless, lung cancer patients treated with osimertinib eventually develop acquired resistance, which is characterized by different mechanisms, either according to EGFR-dependent or EGFR-independent pathways." (PMID 38474400, 2024). "In EGFR-mutant-driven lung cancer: Osimertinib, Afatinib, Capmatinib (OAC)." (PMID 38188499, 2024). "A recent study found a significant association between PM2.5 levels and EGFR-driven lung cancer, which is common among non-smokers and light smokers." (PMID 39727425, 2024). "Researchers have reported EGFR mutations as a good prognostic factor for advanced lung cancer, but not for operable early stage lung adenocarcinoma." (PMID 38783331, 2024). "Comparative analysis of methPLIER-CTD between pan-negative and EGFR-mutated lung cancer patients identified 841 lung cancer pan-negative case-specific DMPs associated with the drug-related gene set and genomic regions of interest." (PMID 38433247, 2024). "Additionally, mTOR activation through an Akt-independent pathway was involved in collagen type I-induced EGFR-TKI resistance in lung cancer cells." (PMID 38397056, 2024). "Lung cancer is a leading cause of mortality worldwide, especially among Asian patients with non-small cell lung cancer (NSCLC) who have epidermal growth factor receptor (EGFR) mutations." (PMID 38794196, 2024). "MTOR inhibition, however, reversed the resistance to EGFR-TKIs in lung cancer." (PMID 38397056, 2024). "This trend may be attributable to the different mutation rates of genes such as EGFR, ALK, and KRAS in younger versus older lung cancer patients." (PMID 38568892, 2024). "To investigate the therapeutic potential of combining EGFR inhibitors with anti-CD47 antibodies, we first examined whether CD47 could be a genuine target for lung cancers bearing driver mutations." (PMID 38483480, 2024). "Another study also found MAPK1 variant, a rare variant in lung cancer, but no other evidence found co-variant with EGFR and PIK3CA." (PMID 38245692, 2024). "Interestingly, the ICC results show that EGFR is primarily localized on the surface of A549 lung cancer cells." (PMID 39453005, 2024). "Additionally, elevated IL-8 levels have been correlated with resistance to EGFR inhibitors and poorer patient outcomes of lung cancer, highlighting its potential as both a therapeutic target and a prognostic biomarker." (PMID 38276239, 2024). "In a more recent study, molecular tests (EGFR and/or ALK activating mutations, and/or ROS1 rearrangements, and/or PD-L1 expression) were performed in 40% of patients with stage III lung cancer and 60% of those with stage IV lung cancer in the Dolnośląskie voivodeship in 2019–2020." (PMID 39518907, 2024). "Conversely, EGFR T790M germline mutations are reported with decreased prevalence in East Asian populations in comparison to North American populations, despite it being the most frequently reported PGV in lung cancer." (PMID 38539485, 2024).
lung cancer (continued). "Some specific lung cancer-associated mutations, in particular, in epidermal growth factor receptor (EGFR), are known to occur more frequently among patients with no history of smoking, and are found as clonal driver mutations in lung adenocarcinomas." (PMID 39021764, 2024). "In addition, miR-218-5p specifically targets EGFR, regulating its expression, and the downregulation of this signaling pathway results in an overexpression of EGFR, a known lung cancer biomarker." (PMID 38473984, 2024). "In conclusion, we identify PCs regulate EGFR mutant lung cancer cells via a paracrine effect." (PMID 39435643, 2024). "In addition, the level of EGFR was also found to be highly upregulated in lung cancer cell lines (A549 and HCC2814) compared to the HEK293 cell line." (PMID 39453005, 2024). "Specifically, lapatinib (0.8 μM), a HER2 inhibitor, was used for breast cancer (MCF7); gefitinib (15 μM), an EGFR inhibitor, for lung cancer (H358); dasatinib (70 nM), an Src inhibitor, for prostate cancer (LNCaP); and finally, AZD1480 (6 μM), a JAK2 inhibitor, for hepatocellular carcinoma." (PMID 38892372, 2024). "Among these, advanced-stage EGFR-positive lung cancer patients typically have a mOS of 45.7 months." (PMID 38402182, 2024). "A549 nonsmall cell lung cancer (NSCLC) cells have more exosomal EGFR than BEAS-2B normal cells." (PMID 38816782, 2024). "Furthermore, a meta‐analysis encompassing data from 22 clinical trials and reported that de novo EGFR T790M was an unfavorable predictive and prognostic marker in the late stage lung cancer." (PMID 38348924, 2024). "For example, EGFR mutations in exon 19 are correlated with high expression of ERCC1 (the oxaliplatin-related gene), low expression of the TYMS gene, and poor prognosis in lung cancer patients." (PMID 38248103, 2024). "Duan has demonstrated that RUSC2 is commonly expressed in diverse lung cancer cells, knockdown of RUSC2 effectively inhibits the migration of lung cancer cells, and RUSC2 regulates the progression of lung cancer through epidermal growth factor receptor (EGFR) signaling." (PMID 38725627, 2024). "We report a case of successful treatment involving the concomitant administration of osimertinib and antituberculosis drugs in an older patient, an 89-year-old female, diagnosed with epidermal growth factor receptor (EGFR)-mutant lung cancer and pulmonary tuberculosis." (PMID 38698706, 2024). "EGFR-TKIs serve as a key class of targeted drugs for lung cancer." (PMID 39196297, 2024). "In this study, we perform a pooled EGFR variant genetic screen to identify erlotinib-responsive and -nonresponsive variants in human models of lung cancer." (PMID 38548752, 2024). "Similarly, concerning lung cancer instances, EGFR gene alterations dictate the selection of tyrosine kinase inhibitors." (PMID 38392565, 2024). "Additionally, certain proteins found on exosome membranes, such as EGFR, placental alkaline phosphatase, EpCam, and Alix, have shown promise as potential prognostic indicators for lung cancer." (PMID 39459055, 2024). "Furthermore, resistance against EGFR inhibitors in lung cancer can be overcome by dual inhibition of MEK and PI3K via activation of p38 signaling." (PMID 38784015, 2024). "For example, EGFR mutant lung cancers may express higher levels of MHC I molecules, while KRAS mutant cancers may express lower levels of CD47 and MHC I molecules." (PMID 38483480, 2024). "Agents, such as EGFR tyrosine kinase inhibitors (TKIs) and ALK inhibitors, have changed the treatment paradigm for patients with actionable mutations, providing a personalized approach to systemic therapy for lung cancer bone metastases." (PMID 39766043, 2024). "Current studies have shown that samples collected from lung cancer patients, including blood plasma, pleural effusion, and bronchoalveolar lavage fluid (BALF), contain EV-DNA with detectable epidermal growth factor receptor (EGFR) mutations (e.g., exon 19 deletion, p.L858R, p.T790M)." (PMID 39402599, 2024).
lung cancer (continued). "The present study demonstrates that DRD1 exerts a tumor suppressive‐like role in lung cancer cells via modulation of EGFR signaling and cell proliferation and that the dopamine network regulates the expression of the immune checkpoint molecule, programmed death‐ligand 1 (PD‐L1)." (PMID 38572507, 2024). "The EGFR L861Q was most frequently appeared in lung cancer patients (18.68%)." (PMID 38245692, 2024). "High CD151 expression levels in non‐small cell lung cancer (NSCLC) patients lacking epidermal growth factor receptor (EGFR) mutations are associated with poorer clinical outcomes." (PMID 38982031, 2024). "For a better understanding of the bioactive mechanisms, four flavonoids (vitexin, kaempferol-3-O-rutinoside, luteolin, and isoorientin) were selected for molecular docking on hallmark protein targets in lung cancer as represented by γ-PI3K, EGFR, and CDK2 through in-silico studies." (PMID 38611505, 2024). "Therefore, it is pertinent to examine the correlation of the EGFR gene with the overall survival of patients with lung cancer." (PMID 39453005, 2024). "Most cases of EGFR‐positive lung cancer are of the lepidic element‐dominant histological subtype." (PMID 38400801, 2024). "The EGFR is a major cancer-predisposition gene with an estimated 31% risk of lung cancer development in non-smoking carriers." (PMID 39199663, 2024). "Therefore, developing ways to target EGFR overexpression appears to be a potentially effective yet previously unexplored strategy for treating lung cancer, which is what we aimed to do in this study." (PMID 39453005, 2024). "Up to 10% of individuals diagnosed with positive epidermal growth factor receptor (EGFR) non‐small cell lung cancer may experience LM, whose median overall survival is only 4–6 weeks if untreated after diagnosis." (PMID 39624075, 2024). "Notably, EGFR plays a role in immune escape by activating and enhancing PD‐L1 expression in lung cancer cells." (PMID 38659399, 2024). "APOBEC3B has been recently involved in lung cancer resistance to anti-EGFR therapy." (PMID 39000238, 2024). "A subset analysis of the Impower150 trial indicated that ABCP may have a benefit on OS compared with bevacizumab plus carboplatin and paclitaxel chemotherapy in EGFR-mutant lung cancer." (PMID 38347279, 2024). "At the protein level, immunoblotting assays illustrated that YY1 was readily detectable in a wide spectrum of oncogene-driven lung cancer cell lines, as well as in most primary tumor samples regardless of EGFR mutation." (PMID 39604408, 2024). "Our extensive interrogation of the spatial and temporal heterogeneity of MET pathway activation upon osimertinib resistance in EGFR-mutant lung cancer may also explain other recent findings from the TATTON study." (PMID 38276867, 2024). "Therefore, our study indicates that pSTAT3-mediated EGFR transcription is a novel molecular mechanism by which lung cancer cells are resistant to EGFR TKIs." (PMID 39967270, 2024). "Recently, Chen et.al (2024) found that while the presence of bone metastasis is a negative prognostic factor for EGFR-mutated lung cancer patients, the addition of antiangiogenic therapy and denosumab, with sequential osimertinib can improve survival outcomes." (PMID 39108772, 2024). "Originally formulated as EGFR inhibitors for lung cancer, these drugs, exemplified by vandetanib, may demonstrate efficacy for lung cancer patients concurrently grappling with SARS-CoV-2-induced diseases." (PMID 38734691, 2024). "What’s more, EGFR expression was inhibited in lung cancer cells with the DHA treatment." (PMID 38778121, 2024). "One of the most relevant examples of lung cancer are the EGFR and KRAS oncogenes." (PMID 38612473, 2024). "Recent investigations have elucidated that alterations in chromatin accessibility mediated by the mammalian SWI/SNF complex may facilitate osimertinib resistance in EGFR-mutant lung cancers." (PMID 39465834, 2024).